STRC (stereocilin)
Description:
Essential to the formation of horizontal top connectors between outer hair cell stereocilia.
Synonyms: DFNB16
Tractability: Antibody: UniProt places it where antibodies can reach, with medium confidence; UniProt predicts a signal peptide or a membrane-spanning region.
Gene: Protein-coding gene on chromosome 15 (43,599,563 to 43,618,800, reverse strand). Ensembl gene ENSG00000242866.
Subcellular location: Cell surface; Cell projection, kinocilium; Cell projection, stereocilium
Pathways (Reactome):
Sensory Perception: Sensory processing of sound by inner hair cells of the cochlea; Sensory processing of sound by outer hair cells of the cochlea
Gene Ontology:
Biological process: auditory receptor cell stereocilium organization; cell-matrix adhesion
Cellular component: cell surface; kinocilium; stereocilium tip; stereocilium
Genetic constraint (gnomAD): Loss-of-function variants: 38 observed, 69.82 expected, observed/expected ratio (o/e) 0.54, 90% interval 0.42 to 0.71. The synonymous counts are far from expectation, so gnomAD's model fits this gene poorly and the ratio says little. Missense variants: 466 observed, 657.13 expected, observed/expected ratio (o/e) 0.71, 90% interval 0.66 to 0.77. Synonymous variants: 172 observed, 259.72 expected, observed/expected ratio (o/e) 0.66, 90% interval 0.58 to 0.75.
Gene-disease validity (ClinGen):
ClinGen rates the evidence that STRC causes each of these diseases.
nonsyndromic genetic hearing loss (autosomal recessive): Definitive.
Homologues: Orthologues: chimpanzee STRC (99% identical), macaque STRC (97% identical), rabbit STRC (91% identical), dog STRC (91% identical), pig STRC (91% identical), mouse Strc (87% identical), rat Strc (87% identical), zebrafish strc (33% identical), tropical clawed frog STRC (31% identical). Paralogues in human: OTOA (13% identical), MSLN (6% identical), MSLNL (5% identical).
Diseases named in the same sentence as STRC in open-access papers:
STRC is named in the same sentence as 27 diseases in open-access papers, as found by Europe PMC text mining. Sharing a sentence is not in itself a finding about the gene and the disease. The quoted sentences say what the papers report.
deafness (29 papers, 2014 to 2026). An inherited or acquired condition characterized by the complete loss of the ability to hear from one or both ears. "The aim of this study was to develop a durable and effective gene therapy for DFNB16, the second most common genetic cause of deafness in humans, caused by mutations of the STRC gene." (PMID 41508981, 2026). "DFNB16 is a recessive form of mild‐to‐moderate human deafness caused by mutations of the stereocilin (STRC) gene, accounting for approximately 11% of all reported cases." (PMID 41508981, 2026). "We used a stereocilin‐deficient mouse line (Strc−/−) with the key characteristics observed in human DFNB16 deafness to model this condition." (PMID 41508981, 2026). "One such example is the contiguous gene deletion of CATSPER2 and STRC genes, previously associated with deafness‐infertility syndrome (DIS) in males." (PMID 38884051, 2024). "The characteristic feature of syndromic male infertility is the presence of mutations in the genetic locus encompassing the CATSPER2 gene, along with neighboring genes like STRC (stereocilin), which have been implicated in deafness." (PMID 39469589, 2024). "Recently, the STRC gene has been suggested to be an important molecular cause of mild-to-moderate deafness." (PMID 36568381, 2022). "Due to racial differences and insufficient attention, the role of STRC gene mutations in the pathogenic of hereditary deafness in China is less reported." (PMID 36504663, 2022). "The main goal was to identify the molecular causes of hearing loss in additional deafness genes, and in particular in the recently added STRC gene." (PMID 36672845, 2022). "Stereocilin is an essential stereociliary protein in the OHCs, the mutation of which in humans causes autosomal recessive non-syndromic deafness." (PMID 36104704, 2022). "The study indicates that, after the GJB2 gene which is the majority of mild to moderate inherited deafness, STRC deletion accounts for the second most common cause." (PMID 36504663, 2022). "Large deletions on chromosome 15 including the Catsper gene, and another gene also associated with spermatozoa, STRC (stereocilin), have also been linked to a rare condition characterized by male infertility and deafness." (PMID 33101214, 2020). "Of the 80 children with congenital bilateral hearing loss in the study, 59 (74%) were found to have genetic variants that may cause congenital deafness, including 44 with GJB2 or SLC26A4 gene variant, 1 with STRC gene variant, and 14 with other genetic variants that may cause deafness." (PMID 36142981, 2022). "Strc−/− mice, which lack stereocilin, display severe to profound deafness and constitute a relevant preclinical model for DFNB16." (PMID 41508981, 2026). "So far, CNVs have been reported in 29 non-syndromic HL-related genes, with STRC, OTOA, and GJB2/GJB6 being the most well-known genes with deafness-causing CNVs." (PMID 35710363, 2022). "Two deafness-related genes (STRC and OTOA) have homologous regions in the human genome, which explains their low coverage in our WGS data." (PMID 35571039, 2022). "Homozygous deletion of both STRC and CATSPER2 has been reported to be associated with deafness-infertility syndrome (OMIM: 61102)." (PMID 35248088, 2022). "For instance, 4 male children had homozygous multigene deletion that involved STRC and CATSPER2, placing them at increased risk of deafness-infertility syndrome, which causes HL and infertility." (PMID 36166228, 2022). "Further analysis of these 11 families for deafness associated infertility genes such as FOXI1, CATSPER2 and STRC could possibly throw more light on the etiology of this phenotype." (PMID 29921236, 2018). "STRC deletions are reported in approximately 1% of mixed deafness populations, making it as a major contributor to congenital hearing impairment, and can cause autosomal recessive NSHL or Deafness-infertility syndrome (DIS) in males if the adjacent CATSPER2 gene is also involved in the deletion." (PMID 30622556, 2018).
deafness (continued). "It was suspected that variants in few genes like STRC, GJB2, SLC26A4, OTOG or TECTA may explain the hearing loss for the majority of individuals in our cohort as is the case in many other world populations for the individuals with moderate to severe deafness." (PMID 32681043, 2020). "In Family 44, a homozygous deletion involving STRC and CATSPER2, leading to deafness–infertility syndrome (OMIM #611102), was identified through GS utilizing our newly developed analytic pipeline." (PMID 40225913, 2024). "Several studies have shown that STRC and OTOA are two of the deafness genes that are more prone to CNVs." (PMID 36597107, 2023). "Contiguous gene deletion syndrome on chromosome 15q15.3, including STRC and CATSPER2, as identified in patient 15, is responsible for a deafness-infertility syndrome." (PMID 34440452, 2021). "Segdups, defined as regions with > 95% homology, are features that are causally implicated in recurrent CNVs mediated by NAHR and were identified in seven deafness genes: TSPEAR (4 segdups), OTOA, STRC, MYO3A, ESPN, OTOGL, CACNA1D." (PMID 24963352, 2014). "In the sample of patients with NSHL, syndromes such as Pendred syndrome (six in the SLC26A4 gene), deafness, and male infertility syndrome (DIS) (three males and two females with NSHL with bi-allelic gross deletions in the STRC and CATSPER2 genes) were also found." (PMID 36555390, 2022).
hearing loss (23 papers, 2014 to 2026). "DFNB16, the second most common genetic cause of hearing loss, is caused by mutations of the STRC gene encoding stereocilin, a protein essential for the effective functioning of outer hair cells (OHCs) as cochlear amplifiers." (PMID 41508981, 2026). "The Stereocilin (STRC) gene, also known as DFNB16, is considered a significant contributor to bilateral mild-to-moderate sensorineural hearing loss." (PMID 38525683, 2024). "Mutations in the STRC gene are the second most common cause of autosomal recessive non-syndromic deafness, and they are particularly prevalent in genetic hearing loss affecting sensory hair cells." (PMID 38525683, 2024). "The STRC gene has been shown to be the most commonly mutated gene in patients with this type of hearing impairment." (PMID 36672845, 2022). "CNV analysis revealed the CNV of the STRC gene is the second most common etiology in cases of mild-to-moderate hearing loss after the GJB2 gene." (PMID 34599366, 2022). "The hearing loss in four other patients was caused by pathogenic biallelic variants in the well-known hearing loss-causing genes: STRC (OMIM 606440); MYO15A (OMIM 602666); SLC26A4 (OMIM 605646); and LOXHD1 (OMIM 613072)." (PMID 34062854, 2021). "Further, we chose to focus on the STRC gene, as it is one of the most common causes of autosomal recessive non-syndromic hearing loss and is often included in NGS-based panel testing." (PMID 32000839, 2020). "In conclusion, STRC copy number deletion was detected in approximately 1% of the Japanese healthy controls, whereas STRC was the causal gene in more than 3% of patients with mild-to-moderate hearing loss in Japan." (PMID 31645979, 2019). "In conclusion, our results show that STRC deletions are the second most common cause of mild-to-moderate hearing loss after the GJB2 gene, which accounts for the majority of genetic hearing loss." (PMID 30867468, 2019). "The STRC gene is a known deafness-associated gene causing mild-to-moderate hearing loss, and is a part of a large deletion in chromosome 15q15.3 at the DFNB16 locus." (PMID 30867468, 2019). "NDST3 and STRC are the risk genes for schizophrenia and hearing impairment that are identified by GWAS, respectively." (PMID 26136833, 2015). "In this study, we identified homozygous deletions of the STRC gene (a 2 copy number loss) in 231 of 9956 Japanese hearing loss patients (2.32%; 231/9956), and 41 cases with a 1 copy number loss of the STRC gene which also carried SNVs in the trans allele configuration." (PMID 35022556, 2022). "Among 108 cases with a 2 copy loss of the whole CKMT1B-STRC-CATSPER2 gene region, 52 cases were male and the prevalence of DIS in patients with hearing loss associated with a 2 copy number loss of the STRC gene was estimated to be 37.1% (52/140)." (PMID 35022556, 2022). "Despite this genetic heterogeneity, the majority of non-syndromic hearing loss is caused by two genes: gap junction protein β2 (GJB2) and stereocilin (STRC)." (PMID 32733828, 2020). "In the evaluation of CNV, one copy number alteration residing in STRC and CATSPER2, which are both known hearing loss genes, was detected by both EXCAVATOR2 and in-house CNV tool from only SB246–482." (PMID 29482514, 2018). "GS of the remaining 15 cases yielded diagnoses in three individuals, including the identification of deletions in LOXHD1 and STRC, and a recently characterized 125 kb deletion overlapping CRYL1, which refines a critical upstream regulatory region associated with GJB2-related hearing loss." (PMID 41367487, 2025). "In patients with previous negative molecular diagnostics for non-syndromic, mild to moderately severe hearing loss, the STRC gene should be analysed in case it was not performed in the past." (PMID 36672845, 2022).
hearing loss (continued). "High-resolution genome-wide CNV analysis of 150 cases and 157 controls revealed deletions in genes known to be involved in hearing (e.g. GJB6, OTOA, and STRC, encoding connexin 30, otoancorin, and stereocilin, respectively), supporting CNV contributions to hearing loss phenotypes." (PMID 25528277, 2014). "While STRC mutations lead to the loss of top connectors, disorganized hair bundle morphologies, and bundles detached from the tectorial membrane, this study revealed that STRC mutations did not cause early hair cell death, unlike other hearing loss mutations." (PMID 38525683, 2024).
deafness-infertility syndrome (7 papers, 2013 to 2025). Deafness-infertility syndrome (DIS) is a very rare syndrome associating sensorineural deafness and male infertility. "The gene CATSPER2, a neighboring gene to STRC, is responsible for sperm motility and leads to deafness infertility syndrome in males, most commonly with sequential deletion of both STRC and CATSPER2 genes." (PMID 36504663, 2022). "In another instance, monozygotic twin brothers, aged 30, diagnosed with Deafness-Infertility Syndrome (DIS), were found to have a homozygous deletion of the STRC gene, resulting in the removal of the CATSPER 2 gene." (PMID 39469589, 2024). "Sensorineural hearing loss and male infertility (Deafness-Infertility Syndrome; DIS) is a contiguous gene deletion syndrome resulting from homozygous deletion of the CATSPER2 (responsible for male infertility) and STRC (responsible for hearing loss) genes on chromosome 15q15.3." (PMID 23648117, 2013).
Infertility (7 papers, 2014 to 2024). "This demonstrates that the infertility phenotype was caused by the homozygous deletion of CATSPER2 alone rather than by deletion of STRC and/or CKMT1B." (PMID 38165034, 2024). "Additionally, because the STRC gene region is associated with a segdup that results in pseudogenes of both STRC and CATSPER2, homozygous deletions of the entire region (STRC and CATSPER2) cause DIS, characterized by mild SNHL in males and females and sperm motility defects and infertility in males." (PMID 24963352, 2014). "Moreover, the infertility phenotype of patients with homozygous deletion of CATSPER2 (patient C5), homozygous deletion of CATSPER2 combined with heterozygous deletion of STRC and CKMT1B (patients C6–C8), or homozygous deletion of CATSPER2, STRC, and CKMT1B (patients C1–C4) was indistinguishable." (PMID 38165034, 2024).
male infertility (7 papers, 2013 to 2025). The inability of the male to effect fertilization of an ovum after a specified period of unprotected intercourse. "Genetic heterogeneity is one cause of homozygous copy number variants (CNVs) involving the CATSPER2 and STRC genes, which are associated with DIS and male infertility." (PMID 41254778, 2025). "Consequently, patients with a STRC deletion might also possess a CATSPER2 deletion that could be involved in hearing loss and male infertility." (PMID 30867468, 2019).
sensorineural hearing loss (2 papers, 2025). "Autosomal recessive sensorineural hearing loss associated with the STRC gene is the second most common cause of hereditary sensorineural hearing loss after GJB2 mutations, accounting for approximately 2–8% of cases depending on the population studied." (PMID 41562875, 2025). "Variants in the STRC gene results in syndromic sensorineural hearing loss (SNHL), due to the fact that some variants are associated with the CATSPER gene, while variants in the GJB2 gene are mainly related to nonsyndromic SNHL." (PMID 41254778, 2025).
schizophrenia (1 paper, 2015). A major psychotic disorder characterized by abnormalities in the perception or expression of reality. "In the candidate CNV regions, 26 regions had no overlaps with the common CNVs found in Asian populations and included the genes (i.e., ANTXRL, CHST9, DNM3, NDST3, SDK1, STRC, SKY) that are associated with schizophrenia and/or other psychiatric diseases." (PMID 26136833, 2015).
Usher syndrome type 3A (1 paper, 2022). Any Usher syndrome in which the cause of the disease is a mutation in the CLRN1 gene. "Aside from DFNB9, current efforts target Usher Syndrome Type 3A (defects of CLRN1 coding for clarin‐1), DFNB8 (defects of TMRPSS3 coding for Transmembrane protease serine 3), and DFNB16 (defects of STRC coding for stereocilin)." (PMID 35833443, 2022).
neurological diseases (1 paper, 2013). "Remarkably, about 13% of the DEGs in FGF2 treated S252W fibroblasts were associated with neurological diseases (BAT3, HS6ST1, IFI44L, RFC3, RPS9, STRC and TCF19)." (PMID 23593218, 2013). "Seven (12.7%) of the DEGs were associated with neurological diseases (BAT3, HS6ST1, IFI44L, RFC3, RPS9, STRC and TCF19) according to the IPA analysis (p = 0.003)." (PMID 23593218, 2013).
STRC also shares sentences with these, for which no sentence is quoted: Hearing impairment (3 papers); Bloom syndrome (2); congenital ichthyosis (2); autosomal recessive deafness-16 (1); cancer (1); CHARGE syndrome (1); congenital hypothyroidism (1); endocarditis (1); hereditary spastic paraplegia type 11 (1); inherited diseases (1); Meniere disease (1); nonsyndromic deafness (1); Pendred syndrome (1); periventricular nodular heterotopia (1); psychiatric diseases (1); sarcoma (1); spinal muscular atrophy (1); Tay-Sachs disease (1).